DNAJB2 (DnaJ heat shock protein family (Hsp40) member B2)
Description:
Functions as a co-chaperone, regulating the substrate binding and activating the ATPase activity of chaperones of the HSP70/heat shock protein 70 family. In parallel, also contributes to the ubiquitin-dependent proteasomal degradation of misfolded proteins. Thereby, may regulate the aggregation and promote the functional recovery of misfolded proteins like HTT, MC4R, PRKN, RHO and SOD1 and be crucial for many biological processes. Isoform 1 which is localized to the endoplasmic reticulum membranes may specifically function in ER-associated protein degradation of misfolded proteins.
Synonyms: HSJ-1; HSJ1; HSPF3; CMT2T; DSMA5; HMNR5
Tractability: PROTAC: UniProt records ubiquitination sites on it; ubiquitination databases record sites on it; its protein half-life has been measured.
Gene: Protein-coding gene on chromosome 2 (219,279,342 to 219,286,898, forward strand). Ensembl gene ENSG00000135924.
Subcellular location: Cytoplasm (Isoform 2); Nucleus; Endoplasmic reticulum membrane (Isoform 1)
Subcellular location (Human Protein Atlas): Nuclear membrane
Gene Ontology:
Molecular function: ATPase activator activity; Hsp70 protein binding; protein binding; protein serine/threonine kinase binding; protein-folding chaperone binding; ubiquitin binding; ubiquitin-modified protein reader activity
Biological process: negative regulation of cell growth; negative regulation of cell population proliferation; negative regulation of inclusion body assembly; negative regulation of protein binding; positive regulation of ATP-dependent activity; protein folding; protein refolding; regulation of protein folding; regulation of protein ubiquitination; neuron cellular homeostasis; positive regulation of proteasomal ubiquitin-dependent protein catabolic process; response to unfolded protein
Cellular component: cytoplasm; cytosol; endoplasmic reticulum membrane; nuclear membrane; nucleus
Genetic constraint (gnomAD): Loss-of-function variants: 21 observed, 36.16 expected, observed/expected ratio (o/e) 0.58, 90% interval 0.41 to 0.84. The upper end of that interval is the gene's LOEUF score, 0.84, which puts it in group 3 of 6, group 1 being the genes least tolerant of losing a copy. Missense variants: 365 observed, 435.95 expected, observed/expected ratio (o/e) 0.84, 90% interval 0.77 to 0.91. Synonymous variants: 172 observed, 168.23 expected, observed/expected ratio (o/e) 1.02, 90% interval 0.9 to 1.16.
Gene-disease validity (ClinGen):
ClinGen rates the evidence that DNAJB2 causes each of these diseases.
Charcot-Marie-Tooth disease axonal type 2T (autosomal recessive): Definitive. Charcot-Marie-Tooth disease type 2T (CMT2T) is a slowly progressive autosomal recessive sensorimotor peripheral neuropathy with onset in middle age (Higuchi et al., 2016).
Homologues: Orthologues: chimpanzee DNAJB2 (100% identical), rabbit DNAJB2 (91% identical), dog DNAJB2 (88% identical), macaque DNAJB2 (88% identical), rat Dnajb2 (86% identical), pig DNAJB2 (83% identical), guinea pig DNAJB2 (78% identical), mouse Dnajb2 (75% identical), Drosophila melanogaster CG5001 (26% identical), Drosophila melanogaster DnaJ-1 (26% identical), Drosophila melanogaster CG2887 (23% identical), Caenorhabditis elegans dnj-1 (19% identical), and 3 more. Paralogues in human: DNAJB6 (48% identical), DNAJB8 (35% identical), DNAJB7 (34% identical), DNAJB4 (28% identical), DNAJB5 (27% identical), DNAJB1 (26% identical), DNAJB11 (24% identical), DNAJB12 (22% identical), DNAJB13 (22% identical), DNAJB14 (19% identical), DNAJB9 (19% identical).
Diseases named in the same sentence as DNAJB2 in open-access papers:
DNAJB2 is named in the same sentence as 34 diseases in open-access papers, as found by Europe PMC text mining. Sharing a sentence is not in itself a finding about the gene and the disease. The quoted sentences say what the papers report.
neuropathy (6 papers, 2017 to 2026). A disorder affecting the nervous system that manifests with pain, tingling, numbness, and/or muscle weakness. "Disease onset tended to occur later in patients with DNAJB2 variants, who yet developed more severe neuropathy." (PMID 41549766, 2026). "The neuropathy symptoms seen in the proband are similar to those caused by recessive loss-of-function mutations in DNAJB2, albeit with later onset." (PMID 37070754, 2023). "The phenotypic spectrum of DNAJB2-related neuropathies was later broadened by the discovery of two additional mutations of the DNAJB2 gene in patients with dHMN and Charcot-Marie-Tooth disease type 2 (CMT2)." (PMID 28031292, 2017). "Disease onset was typically later in patients with DNAJB2 variants (late adolescence or early adulthood) compared to patients with HINT1 variants (childhood or early adolescence), yet patients with DNAJB2 variants more frequently developed severe neuropathy, as reflected by higher CMTNS scores." (PMID 41549766, 2026). "The downstream mechanisms leading from DNAJB2 loss of function to neuropathy are largely unknown, but accumulation of phosphorylated TARDBP in patient skin biopsies suggests that TARDBP aggregation has a potential role in the pathomechanism." (PMID 37070754, 2023). "Indeed, of the diseases discussed here, only DNAJB2-related neuropathies seem to depend on pure loss of function." (PMID 32093037, 2020). "Symptom onset in patients with DNAJB2‐related neuropathy typically occurs in the second decade of life and manifests as a progressive, primarily distal muscle weakness." (PMID 41549766, 2026). "A Parkinson's disease (PD) phenotype has previously been described as part of the clinical spectrum of DNAJB2‐related neuropathy." (PMID 41549766, 2026). "Finally, neuromyotonia on electromyography, a diagnostic hallmark of HINT1 neuropathy, was not present in any of our patients with DNAJB2 variants but in two patients with HINT1 variants, as expected." (PMID 41549766, 2026). "This study expands the clinical spectrum of DNAJB2‐ and HINT1‐related neuropathies, highlighting distinct non‐motor features and their impact on QoL, and providing the first direct comparison of these two rare axonal disorders." (PMID 41549766, 2026). "Both groups of patients with DNAJB2‐ and HINT1 neuropathy exhibited a CMT2 phenotype." (PMID 41549766, 2026).
distal hereditary motor neuropathy (5 papers, 2013 to 2025). "Mutations in the DNAJB2 gene lead to inherited neuropathies such as Charcot-Marie-Tooth type-2, distal hereditary motor neuropathies, spinal muscular atrophy with parkinsonism and the later stages can resemble amyotrophic lateral sclerosis." (PMID 28031292, 2017). "Here we show that the molecular chaperone, HSJ1 (DNAJB2), mutations in which cause distal hereditary motor neuropathy, can reduce mutant SOD1 aggregation and improve motor neuron survival in mutant SOD1 models of ALS." (PMID 24023695, 2013). "Unlike HSP70, DNAJB2a expression is specifically enriched in neuronal tissues and mutations in DNAJB2 are linked to a rare recessive distal hereditary motor neuropathy and Charcot–Marie–Tooth disease type 2 (Blumenet al., 2012;Gesset al., 2014) implying a critical need for this co-chaperone." (PMID 26936937, 2016). "Mutations in DNAJB2 have been linked to neuromuscular diseases such as distal hereditary motor neuropathy (dHMN) and Charcot-Marie-Tooth disease type 2 (CMT2)." (PMID 40423229, 2025). "Furthermore, HSJ1 appears to be critical for normal motor neuron function, as mutations in DNAJB2 cause recessive distal hereditary motor neuropathy (dHMN)." (PMID 24023695, 2013). "Similar to BAG3 and HSPB8, mutations in the genes coding for DNAJB2, HSPB1 and HSPB3 have been associated with distal hereditary motor neuropathy (dHMN), including Charcot–Marie–Tooth disease." (PMID 40757567, 2023).
Parkinson disease (4 papers, 2017 to 2026). A progressive degenerative disorder of the central nervous system characterized by loss of dopamine producing neurons in the substantia nigra and the presence of Lewy bodies in the substantia nigra and locus coeruleus. "Recessive mutations in the DNAJB2 gene, encoding the J-domain co-chaperones DNAJB2a and DNAJB2b, have previously been reported as the genetic cause of progressive peripheral neuropathies, rarely involving pyramidal signs, parkinsonism and myopathy." (PMID 37070754, 2023). "A further case of dHMN, parkinsonism and cerebellar ataxia due to HSJ1 mutation was recently reported, and a large DNAJB2 gene deletion was found in a family with recessive spinal muscular atrophy and parkinsonism." (PMID 28031292, 2017).
Charcot-Marie-Tooth disease type 2 (2 papers, 2017 to 2025). A Charcot-Marie-Tooth disease characterized by abnormalities in the axon of the peripheral nerve cell. "Another mutation in the J-domain of DNAJB2 is associated with Charcot Marie Tooth disease type 2 (CMT-2), which causes progressive muscle weakness." (PMID 40423229, 2025).
Huntington disease (2 papers, 2023 to 2025). Huntington disease (HD) is a rare neurodegenerative disorder of the central nervous system characterized by unwanted choreatic movements, behavioral and psychiatric disturbances and dementia. "Additionally, we evaluated the therapeutic efficacy of Cystamine, which has been shown to modulate DNAJB2 levels in cellular and animal models of Huntington’s disease." (PMID 40423229, 2025). "In cellular and mouse models of Huntington’s disease, DnaJB2 and DnaJB6 reduce mutant Huntingtin aggregation and delay the onset of Huntington’s disease, whereas other JDPs do not significantly suppress aggregation." (PMID 36581212, 2023).
axonal neuropathies (1 paper, 2026). "In conclusion, we expand the clinical spectrum of DNAJB2‐ and HINT1‐related hereditary neuropathies, describing the phenotype beyond motor symptoms and providing a direct comparison of these two rare axonal neuropathies." (PMID 41549766, 2026).
depression (1 paper, 2026). "All patients with DNAJB2 variants met criteria for depression, while only one patient with HINT1 variants had depression (P4)." (PMID 41549766, 2026). "All patients with DNAJB2 variants fulfilled criteria for depression, compared with one with a HINT1 variant." (PMID 41549766, 2026). "This is in line with our findings, as all of our patients with DNAJB2 variants met the criteria for depression." (PMID 41549766, 2026).
distal myopathy (1 paper, 2024). Distal myopathy refers to a group of muscle diseases which share the clinical pattern of predominant weakness and atrophy beginning in the feet and/or hands. "Variants in SMPX, DNAJB2, and HSPB6 have been identified as a novel cause of late-onset distal myopathy and neuromyopathy." (PMID 39017652, 2024).
experimental autoimmune encephalomyelitis (1 paper, 2022). An autoimmune demyelinating disease of the central nervous system that is produced experimentally in animals by the injection of homogenized brain or spinal cord in Freund's adjuvant. "Moreover, they showed that the miR-155 targeted the heat shock proteins family-40 containing Dnajb1 and Dnajb2, which could regulate Th17 cell differentiation and decrease experimental autoimmune encephalomyelitis and demyelination." (PMID 35676653, 2022).
multiple sclerosis (1 paper, 2022). A progressive autoimmune disorder affecting the central nervous system resulting in demyelination. "The maximum reduction of Dnajb1/Dnajb2/Foxp1/Tnfsf14 network was observed when Multiple sclerosis rats were treated with exercise training and 100 mg/kg Royal jelly (ET-RJ100), but the relative expression of the Hspa4 significantly increased." (PMID 35676653, 2022). "The maximum reduction of the Dnajb1/Dnajb2/Foxp1/Tnfsf14 network was observed when Multiple sclerosis rats were treated with exercise training and 100 mg/kg Royal jelly (ET-RJ100), but the relative expression of the Hspa4 significantly increased." (PMID 35676653, 2022).
cancer (4 papers, 2017 to 2026). A tumor composed of atypical neoplastic, often pleomorphic cells that invade other tissues. "By contrast, HSPB2 negatively correlated with cell proliferation in 20 cancer types, and DNAJB2 negatively correlated with cell proliferation in 18 cancer types." (PMID 33225964, 2020).
tumor (3 papers, 2021 to 2024). "Furthermore, DNA methylation analysis revealed that specific loci in PDX1, EIF2AK4, ASNS, DNAJB2, and FBOX6 were hypomethylated in tumor samples." (PMID 35884393, 2022).
infection (1 paper, 2014). The state of being infected such as from the introduction of a foreign agent such as serum, vaccine, antigenic substance or organism. "For instance, Dnaja2, Dnajb2, Dnajb12a, Dnajb12b, Dnajb14, Dnajc5ab, Dnajc5gb, Dnajc7, Dnajc16, and Dnajc26 were up-regulated only at 3 days after infection, but not at 14 days after infection; similarly, Dnajc28 was up-regulated only at 14 days after infection, but not at 3 days after infection." (PMID 25542027, 2014).
myopathy (1 paper, 2023). A disease of the muscle in which the muscle fibers do not function properly. "Additional studies will be needed to clarify the frequency and mechanisms of myopathy associated with DNAJB2 loss of function." (PMID 37070754, 2023).
neurological disorders (1 paper, 2022). "Of these, SH3BGRL3 has already been linked to SCZ and PSEN1, B9D2, and CXCR5 as well as DNAJB2 and were implicated in other neurological disorders." (PMID 36344995, 2022).
neuromuscular disease (1 paper, 2020). "In this review, we cover mutations in DNAJB6, DNAJB2, αB-crystallin (CRYAB, HSPB5), HSPB1, HSPB3, HSPB8, and BAG3, and discuss the molecular mechanisms by which they cause neuromuscular disease." (PMID 32093037, 2020).
DNAJB2 also shares sentences with these, for which no sentence is quoted: amyotrophic lateral sclerosis (2 papers); Parkinsonism (2); Ataxia (1); breast carcinoma (1); distal motor neuropathy (1); hepatocellular carcinoma (1); Hypoglycemia (1); limb-girdle muscular dystrophy type 1D (1); liver disease (1); neuroblastoma (1); neurodegenerative disease (1); neuromyotonia (1); peripheral neuropathies (1); phenylketonuria (1); polyneuropathy (1); proteinopathy (1); sarcoma (1); spinal muscular atrophy (1).